SNORD38B (small nucleolar RNA, C/D box 38B )
Synonyms: RNU38B; U38B
Gene: Small nucleolar RNA gene on chromosome 1 (44,778,390 to 44,778,458, forward strand). Ensembl gene ENSG00000281859.
Gene Ontology:
Biological process: RNA processing
Cellular component: nucleolus
Homologues: Orthologues: chimpanzee SNORD38B (99% identical), macaque SNORD38B (99% identical), pig SNORD38B (93% identical), rabbit SNORD38B (86% identical), mouse Gm23615 (77% identical). Paralogues in human: SNORD38C (90% identical), SNORD38D (88% identical), SNORD38A (72% identical).